CXCL1 (C-X-C motif chemokine ligand 1)
Diseases named in the same sentence as CXCL1 in open-access papers (continued):
Sharing a sentence is not in itself a finding about the gene and the disease.
triple-negative breast carcinoma (17 papers, 2015 to 2025). An invasive breast carcinoma which is negative for expression of estrogen receptor (ER), progesterone receptor (PR), and human epidermal growth factor receptor 2 (HER2). "CXCL1 has been implicated in various cancers, including triple-negative breast cancer." (PMID 39408697, 2024). "In triple-negative breast cancer cells, there is often an autocrine increase in cell proliferation by CXCL1." (PMID 37108425, 2023). "CXCL1 expression is also increased relative to normal tissue in mesenchymal-like triple-negative breast cancer and basal-like triple-negative breast cancer." (PMID 37108425, 2023). "We and others have previously shown that human triple-negative breast cancers were expressing higher levels of most CXCR2 ligands (CXCL1, 2, 3, 5, 6, 7 and 8) than luminal or Her2-positive tumors." (PMID 32727083, 2020). "Our findings suggest that CXCL1 secreted by hAdSCs elicits doxorubicin resistance through miR-106a-mediated ABCG2 upregulation in triple negative breast cancer." (PMID 28750689, 2017). "CXCL1 secreted by hAdSCs downregulated miR-106a expression in triple negative breast cancer, and resulted in ABCG2 upregulation and doxorubicin resistance." (PMID 28750689, 2017). "In conclusion, our findings suggest that CXCL1 secreted by hAdSCs elicits doxorubicin resistance through miR-106a-mediated ABCG2 upregulation in triple negative breast cancer." (PMID 28750689, 2017). "We propose that in vivo studies using xenograft and syngeneic mouse models combined with CXCL1 neutralizing antibodies could provide valuable insights into the distinct roles of CXCL1 in LDHC-silenced triple negative breast cancer cells." (PMID 40108668, 2025). "High CXCL1 expression in triple-negative breast cancer may be due to transforming growth factor-α (TGF-α)." (PMID 37108425, 2023). "Therefore, further studies are needed to determine whether the increased CXCL1 levels following LDHC knockdown in triple negative breast cancer cells primarily impact tumor growth or immune cell infiltration and activation." (PMID 40108668, 2025). "We recently reported that CXCR2 ligands, potentially growth-related oncogene (GRO) members (CXCL1/2/3), and TGF-β1, which are abundantly secreted by triple-negative breast cancer cells, concertedly induce robust neutrophil migration." (PMID 34567000, 2021). "On the other hand, high CXCL1 expression does not always occur in triple-negative breast cancer cell lines." (PMID 37108425, 2023). "Among them, CXCL1, although it was not the most abundant, increased ABCG2 expression and decreased doxorubicin sensitivity in triple negative breast cancer cells." (PMID 28750689, 2017).
depression (16 papers, 2020 to 2026). "IL-17 A-induced inflammatory mediators, including IL-6, IL-1β, Ptgs2, Csf2, and Cxcl1, can cause myocardial inflammation and depression [,14], and have been associated with endotoxin-induced cardiac dysfunction and shock [14,]." (PMID 41311862, 2025). "The CXCL1 chemokine deletion can cause rat depression-like behaviors, and CXCL1/CXCL2 correlates with depression-like behavior in response to chronic stress." (PMID 35711916, 2022). "It is possible that, as in experimental animals, depression is associated with an increase in CXCL1 expression in this brain structure in humans." (PMID 35457023, 2022). "If, in contrast, the human hippocampus showed a decrease in CXCL1 expression, it would indicate that CXCL1 plays an important role in brain function in humans and a decrease in the expression of this chemokine could cause depression." (PMID 35457023, 2022). "Previous studies and our data also confirmed that depression promotes an increase in CXCL1 levels in the TME." (PMID 40839237, 2025). "Compared with healthy subjects, patients with suicidal depression had significantly decreased mRNA expressions of chemokines in the prefrontal cortex, including CXCL1." (PMID 36561317, 2022). "It has been demonstrated that the upregulation of the chemokine CXCL1 in the hippocampus participated in depression development." (PMID 36561317, 2022). "The mechanism of CXCL1 involvement in major depression in humans appears to differ significantly from the animal model." (PMID 35457023, 2022). "Studies have shown that the main source of IL-8 and CXCL1 is macrophages, suggesting that depression may promote IL-8 and CXCL1 secretion by inducing macrophage proliferation and activation." (PMID 40839237, 2025). "It seems that the decreased expressions of CXCL1 and CCR7 will increase the risk of depression." (PMID 36561317, 2022). "CXCL1 upregulation can contribute to the maintenance of neuropathic pain and may play a critical role in stress-induced depression, which can be observed predominantly in patients with SCI occurring in the C region." (PMID 33806460, 2021). "Previous studies indicated that CXCL1 might participate in the pathogenesis of depression." (PMID 32513185, 2020). "For instance, Hyperoside significantly mitigates depression-like behaviors in chronic stress-induced mice by inhibiting the NLRP1 inflammasome and modulating the CXCL1/CXCR2/BDNF signaling pathway, leading to improved anhedonia and reduced immobility time." (PMID 40444002, 2025). "Among their top 10 most significant proteins that were altered after treatment were the same proteins that we found in our OPLS and OPLS-DA models for depression and anxiety (CXCL6, STAMPB, CXCL1, SIRT2, AXIN1, CXCL5, ST1A1, and IL-7)." (PMID 36979692, 2023). "To research the influence of Hyp on the depression-like behavior of mice mediated by the NLRP1 inflammasome, we detected the mRNA levels of CXCL1, CXCR2, and BDNF in the hippocampus of mice." (PMID 36556951, 2022). "CXCL1 and VEGF have been shown to contribute to chronic stress-induced depression in rodent models." (PMID 39595087, 2024). "Our results showed that chronic stress, inducing depression-like behaviors in mice, led to increased levels of TNF-α, TNFR1, C3, CXCL1, and cleaved-caspase-3, indicating that astrocyte activation and neuronal apoptosis occurred during these depression-like behaviors." (PMID 38710713, 2024). "Nevertheless, the results of the current study suggest that in a mouse model of depression (BDNF+/−), CXCL1 deletion and Slc17a7 reduction are related to the loss of excitatory neurons in the prefrontal lobe, whereas Ptbp1 downregulation correlates with neuronal regeneration." (PMID 35711916, 2022). "There are no studies showing correlations between depression on CXCL1 expression in the hippocampus in humans." (PMID 35457023, 2022).
depression (continued). "One paper shows that in elderly patients, plasma CXCL1 may be slightly increased in depression, although the results were not statistically significant." (PMID 35457023, 2022).
ischemic stroke (16 papers, 2015 to 2025). A stroke disorder caused by obstruction of blood flow to the brain, due to thrombotic (local blood clot formation) or embolic (due to a blood clot or other material traveling from another site) event. "Therefore, individuals with the T allele of rs3117604, which is located in the CXCL1 promoter, have an increased predisposition to ischemic stroke." (PMID 35457023, 2022). "In rats, an ischemic stroke is associated with promoter hypermethylation of miR-532-5p, which reduces the expression of the miRNA that is directly downregulating the expression of the rat paralog for human CXCL1." (PMID 35457023, 2022). "CXCL1 expression has been found to be closely associated with ischemic stroke." (PMID 35457023, 2022). "CXCL1, as a neutrophil‐specific chemokine, improves neurological outcomes in experimental ischemic stroke." (PMID 37122157, 2023). "Neutrophil recruitment via CXCL1 is differentially regulated by interleukin (IL)-17+ γδ T cells, which promote CXCL1 production by astrocytes in murine models of ischaemic stroke." (PMID 36346451, 2023). "We focused on the cytokine CXCL1, a neutrophil attractant chemokine in ischemic stroke, multiple sclerosis and multiple murine models of neuroinflammation." (PMID 37280283, 2023). "Nevertheless, depending on the literature cited, CXCL1 levels in the blood in patients with ischemic stroke are either unchanged or lower." (PMID 35457023, 2022). "Patients with ischemic stroke have elevated levels of CXCL1 in cerebrospinal fluid and at the same time CXCL1 levels are associated with the extent of ischemic stroke." (PMID 35457023, 2022). "The chemokine released during the acute phase of ischemic stroke is chemokine group CXC ligand 1 (CXCL1), also known as GRO or KC, secreted mainly by macrophages and endothelial cells." (PMID 31514749, 2019). "In response to inflammatory mediators (e.g., tumor necrosis factor-α, interferon-γ), neutrophils and macrophages produce CXCL-1, which exerts neutrophil-chemoattractant activity during the early phase of ischemic stroke." (PMID 31083528, 2019). "Among the upregulated genes, Hspa1b, Ccl2, Cxcl2, Ccl3, Serpina3n, Timp1, H19, Hspb1, Ccl20, and Cxcl1 were found to demonstrate significant upregulation in pathological phase of ischemic stroke." (PMID 25861363, 2015). "Notably, increased CXCL1 levels have been reported in the CSF samples of ischaemic stroke patients, supporting a potential translational role for the chemokine in human subjects." (PMID 36346451, 2023). "Increased CXCL1 expression has also been shown in brain tissue affected by ischaemic stroke." (PMID 35457023, 2022). "In women with ischaemic stroke, CXCL1 levels in the blood are lower, while in men they are higher." (PMID 35457023, 2022). "Future work will explore whether blockade of the potential mediators of enhanced neutrophil pathogenicity (IL-6, CXCL1) identified in these experiments can ameliorate the worse ischemic stroke outcomes seen in aged animals." (PMID 31927534, 2020). "In summary, ischemic stroke results in upregulated expression of adhesion molecules (P‐selectin, E‐selectin, and ICAM‐1) and chemokines (CCL‐2, CCL‐3, CCL‐4, CCL‐5, and CXCL‐1)." (PMID 37122157, 2023). "Our results have revealed that ischemic stroke results in upregulated expression of adhesion molecules (P‐selectin, E‐selectin, and ICAM‐1) and chemokines (CCL‐2, CCL‐3, CCL‐4, CCL‐5, and CXCL‐1)." (PMID 37122157, 2023). "Ischemic stroke induces the release of different chemokines such as CCL-2, CCL-3, CCL-4, CCL7, CCL-11, CXCL-1, CXCL10, from the ischemic tissue." (PMID 30584250, 2018).
multiple sclerosis (16 papers, 2012 to 2025). A progressive autoimmune disorder affecting the central nervous system resulting in demyelination. "This indicates that CXCL1 may be associated with poor mental status and sickness behaviors of patients with multiple sclerosis, as well as other neuroinflammatory diseases." (PMID 35457023, 2022). "Finally, CXCL1 can inhibit multiple sclerosis by causing neutrophil infiltration into the brain." (PMID 35457023, 2022). "We have reported that IL-17 plays a pathogenic role in experimental autoimmune encephalomyelitis, a mouse model of multiple sclerosis, promoting the recruitment of neutrophils and inflammatory monocytes to the CNS via CXCL1 production." (PMID 39897939, 2025). "Nevertheless, it seems that the destructive properties of CXCL1 are predominant, as in patients with multiple sclerosis, plasma CXCL1 levels are correlated with clinical disability." (PMID 35457023, 2022). "Elevated CXCL1 levels have also been shown in multiple sclerosis patients in blood and cerebrospinal fluid." (PMID 35457023, 2022). "In multiple sclerosis, an increase in CXCL1 expression in the brain has a destructive effect on neural tissue through infiltration of neural tissue by neutrophils." (PMID 35457023, 2022). "In the CNS, however, CXCL1 astrocyte expression has already been shown in animal models after brain and spinal cord injury, as well as in humans with multiple sclerosis." (PMID 31616413, 2019). "CXCL1 has been reported to be overexpressed in gastric, colon, and skin cancers and is known to recruit oligodendrocytes in multiple sclerosis when coupled with CXCR2." (PMID 27812125, 2016). "In multiple sclerosis, the upregulation of CXCL1 was induced by proinflammatory cytokines such as IL-1 beta and IFN-gamma and those cytokines were also increased in a streptozotocin-induced diabetic neuropathy model." (PMID 25789329, 2015). "CXCL1 is also selectively expressed in hypertropic astrocytes after active multiple sclerosis lesions in humans." (PMID 24580964, 2014). "CXCL1 expression is increased in the brains of patients with multiple sclerosis." (PMID 35457023, 2022). "There are also indications that CXCL1 expression and disease progression in patients with multiple sclerosis may also be inhibited by IFN-γ." (PMID 35457023, 2022). "This discrepancy may be due to the fact that CXCL1 could be a significant factor in the development of multiple sclerosis in just the early stages of the disease." (PMID 35457023, 2022). "In multiple sclerosis, CXCL1 is produced by activated microglia and astrocytes." (PMID 35457023, 2022). "However, as it is very difficult to find the exact counterparts of these two CXC chemokines, there is a need for experiments investigating the effect of IFN-γ on CXCL1 expression in human neural tissue during multiple sclerosis." (PMID 35457023, 2022). "CXCL1 is a significant element in the course of multiple sclerosis." (PMID 35457023, 2022). "CXCL1 also participates in the progression of multiple sclerosis." (PMID 35457023, 2022). "It is of note that in a mouse model of multiple sclerosis, astrocyte‐specific induction of CXCL1 augmented disease progression via recruitment of neutrophils 54, while in an AD‐like mouse model, blocking the entry of neutrophils into the brain was shown to have a beneficial effect upon pathogenesis." (PMID 32003148, 2020). "For instance, in the case of autoimmune diseases, such as multiple sclerosis or experimental autoimmune encephalomyelitis, neutrophils are known to be attracted by the release of CXCL1, CXCL2, and CXCL5, which are in turn stimulated by different molecules, such as IL-17 or IFN-γ." (PMID 33364241, 2020). "This study identifies CXCL1 not only as a key regulator of granulocyte recruitment into the CNS, but also as a new potential target for the treatment of neuroinflammatory diseases such as multiple sclerosis." (PMID 22269426, 2012).
multiple sclerosis (continued). "KC (CXCL1) is a chemokine protein that plays a pleiotropic role inside the CNS-it might act as a chemoattractant for neutrophils, but it was also proven to have immunoprotective properties in multiple sclerosis." (PMID 34359973, 2021). "CXCL1, CXCL2, and CXCL8/IL-8 are contributors to granulocyte and leukocyte migration, particularly in other autoimmune diseases such as multiple sclerosis and experimental autoimmune encephalomyelitis." (PMID 35885983, 2022).
rheumatoid arthritis (16 papers, 2015 to 2025). A chronic, systemic autoimmune disorder characterized by inflammation in the synovial membranes and articular surfaces. "Cxcl1, and its cognate receptor Cxcr2, are commonly associated with recruitment of neutrophils from the vascular supplies, and signaling via this receptor is implicated in the pathogenesis of rheumatoid arthritis, lung injury, and adenoviral keratitis." (PMID 25595590, 2015). "At the same time, CXCL1 expression in synovial fluid is higher in patients with rheumatoid arthritis than in those with osteoarthritis." (PMID 35457023, 2022). "In FLS, the expression of CXCL1 is also increased by resistin, an adipokine produced by macrophages located in the synovium in patients with rheumatoid arthritis." (PMID 35457023, 2022). "The synovial fluid in patients with rheumatoid arthritis also show increased levels of IL-17, a cytokine that increases CXCL1 expression, particularly in FLS." (PMID 35457023, 2022). "Further, a recent clinical trial observed a significant reduction in serum CXCL1 protein expression following treatment with an anti-inflammatory agent in rheumatoid arthritis patients." (PMID 35833018, 2022). "The Enrichr pathway assignment analysis (KEGG 2021 Human database) additionally revealed enrichment of chemokine encoding genes (CXCL1, CXCL2, CXCL3, CXCL6, CXCL5, CXCL8, CCL2) which were aligned to several pathways like amoebiasis and rheumatoid arthritis." (PMID 35646693, 2022). "One component of the pathophysiology of rheumatoid arthritis is an increase in CXCL1 expression in rheumatoid arthritis patients in the blood and synovial fluid." (PMID 35457023, 2022). "However, the importance of CXCL1 in the destruction of bone tissue in the joints of patients with rheumatoid arthritis is yet to be thoroughly investigated." (PMID 35457023, 2022). "CXCL1 participates in rheumatoid arthritis by acting on various cells in the joints." (PMID 35457023, 2022). "Previous studies have reported that CXCL1 contributes to the ingress of neutrophils into rheumatoid arthritis (RA) joint, and during cartilage development, CXCL1 induces chondrocyte hypertrophy and apoptosis." (PMID 34917160, 2021). "FLS increases the expression of CXCL1 under the influence of pro-inflammatory cytokines such as TNF-α and IL-1β, whose expression is also increased in rheumatoid arthritis patients." (PMID 35457023, 2022). "In our study, a significant proportion of genes elevated by IL-1B and IL-36 belonged to the KEGG rheumatoid arthritis pathway (e.g., CCL20, CXCL7, and CXCL1)." (PMID 29434599, 2018). "Notably, in T cells, IL-17A/F, TNF-α, and CXCL1/2 were upregulated in LKP-treated mice, with KEGG enrichment of IL-17 and TNF signaling pathways, consistent with findings in rheumatoid arthritis where IL-17-producing Th17 cells drive synovial inflammation." (PMID 41459160, 2025). "Interestingly, the five cytokines (CCL2, CCL3, CCL20, CXCL1, and IL8) that are involved in the leukocyte infiltration in the blood vessel of rheumatoid arthritis patients are also found in the xenoAMP(S)-poly(I:C) activated HDMVEC." (PMID 38306481, 2024). "CXCL1 also increases the production of IL-6 in FLS, one of the factors causing an increase in IL-6 in synovial fluid in patients with rheumatoid arthritis; such a response does not occur in healthy individuals." (PMID 35457023, 2022). "The chemokines CXCL1 and CXCL6 are chemotactic cytokines involved in various pathological processes including inflammatory diseases, and it has been shown that both CXCL1, CXCL6, and SEMA7A are involved in the inflammatory response in joint-related diseases such as rheumatoid arthritis." (PMID 32434555, 2020).